PCSK9 (proprotein convertase subtilisin/kexin type 9)
Diseases named in the same sentence as PCSK9 in open-access papers (continued):
Sharing a sentence is not in itself a finding about the gene and the disease.
Hypercholesterolemia (continued). "PCSK9 inhibition is an upcoming therapeutic target for patients with hypercholesterolemia and due to the high coincidence of heart failure in this population, it is important to understand the role of oxLDL, LOX-1, and PCSK9 in cardiomyocytes." (PMID 28913715, 2017). "PCSK9 has become one of the most promising therapeutic targets for hypercholesterolemia and ischemic CVD." (PMID 28970592, 2017). "Three weeks after injury, when a mature intimal hyperplasia had been formed, hypercholesterolemia was induced by a single injection of PCSK9 virus and a switch to western HFD." (PMID 28716818, 2017). "For predicting combined hypercholesterolemia, the values of AUC by sdLDL-C, apoC3, and PCSK9 were 0.919, 95% CI 0.891-0.946; 0.879, 95% CI 0.848-0.911; and 0.606, 95% CI 0.563-0.648; respectively (all p < 0.001)." (PMID 27713142, 2017). "The link between PCSK9 and plasma LDL-C levels was first established by the discovery of missense mutations in PCSK9 in patients with an autosomal dominant form of familial hypercholesterolemia." (PMID 28817679, 2017). "The efficiency and safety of PCSK9 inhibitor therapy for hypercholesterolemia has been evaluated, but a pooled analysis of the therapy for FH is lacking." (PMID 27458166, 2017). "Proprotein convertase-subtilisin/kexin type 9 (PCSK9) monoclonal antibody is a new therapy to reduce low-density lipoprotein cholesterol (LDL-C) level in patients with familial hypercholesterolemia (FH)." (PMID 27458166, 2017). "Previous studies have reported high plasma concentrations of both intestinal apolipoprotein (apo) B-48-containing lipoproteins and PCSK9 in subjects with familial hypercholesterolemia (FH)." (PMID 28619117, 2017). "Proprotein convertase subtilisin/kexin type 9 (PCSK9) has been recently identified as a new useful target for hypercholesterolemia treatment." (PMID 27424515, 2016). "Our findings, presented here for the first time, provide new information about coordinated up-regulation of liver Pcsk9 and Srebf-2 genes expression leading to hypercholesterolemia observed in experimental CRF." (PMID 26481479, 2016). "In this context, proprotein convertase subtilisin/kexin type 9 (PCSK9) has been recently identified as a new useful target for hypercholesterolemia treatment." (PMID 27424515, 2016). "In the present study, to gain a better insight into the role of PCSK9 in a development of CRF-related hypercholesterolemia, we examined liver Pcsk9 gene expression in rat model of this disease." (PMID 26481479, 2016). "Although the PCSK9 locus is polymorphic, evidence has not yet emerged to suggest that routine genetic testing would predict responsiveness to PCSK9 inhibition, in patients with primary hypercholesterolaemia." (PMID 27095708, 2016). "With LDLC lowering potency well beyond statins, PCSK9 inhibitors now offer the promise of optimizing LDLC in a majority of patients with heterozygous familial hypercholesterolemia (HeFH), cardiovascular disease (CVD), and statin intolerance." (PMID 27538393, 2016).
Hypercholesterolemia (continued). "Alirocumab is a fully human monoclonal antibody to proprotein convertase subtilisin kexin type 9 (PCSK9) under investigation for treatment of hypercholesterolemia and reduction of cardiovascular events." (PMID 25240705, 2014). "Alirocumab is a fully-human, monoclonal antibody targeted to proprotein convertase subtilisin/kexin type 9 currently in Phase 3 development for the treatment of hypercholesterolemia." (PMID 24842558, 2014). "Alirocumab (formerly REGN727/SAR236553; Sanofi-Regeneron) is a fully human, monoclonal antibody targeted to PCSK9 currently in Phase 3 development for the treatment of hypercholesterolemia." (PMID 24842558, 2014). "In human, gain-of-function mutations in the PCSK9 gene caused a high LDL-C level and a form of familial hypercholesterolemia, whereas loss-of-function variants lead to a low LDL-C level and a reduced incidence of CAD." (PMID 25496400, 2014). "The positive associations of the plasma PCSK9 levels with TC and LDL-C were previously observed in patients with familial hypercholesterolemia and CAD, even in the healthy subjects." (PMID 25496400, 2014). "PCSK9 (Proprotein Convertase Subtilisin Kexin type 9) is a circulating protein that promotes hypercholesterolemia by decreasing hepatic LDL receptor protein." (PMID 23298392, 2013). "Co-treatment of PCSK9 inhibitors with drugs that suppress cholesterol synthesis is even more effective in reducing LDL cholesterol in hypercholesterolemia patients." (PMID 23883163, 2013). "Recently, a new Yucatan minipig model of familial hypercholesterolemia was created by DNA transposition of human D374Y-proprotein convertase subtilisin/kexin type 9 (PCSK9) gain-of-function mutant." (PMID 23844374, 2013). "Here we review the four models of porcine atherosclerosis, including the diabetic/hypercholesterolemic model, Rapacz-familial hypercholesterolemia pig, the (PCSK9) gain-of-function mutant pig model, and the Ossabaw miniature pig model of metabolic syndrome." (PMID 23844374, 2013). "The possibility of using PCSK9 in the treatment of hypercholesterolemia has fueled considerable research into related molecular mechanisms." (PMID 22794791, 2012). "This also provided a proof of principle that PCSK9 is a promising and safe target to treat hypercholesterolemia and prevent CAD." (PMID 22848640, 2012). "Familial Hypercholesterolemia results from mutations in the LDL receptor, ApoB, PCSK9, and ApoE genes." (PMID 22111029, 2012). "The discovery of PCSK9 and its genetic relation to hypercholesterolemia led to a very exciting and active period of identification of the mechanisms of action of PCSK9, and to the development of powerful animal genetic models." (PMID 22848640, 2012). "The proprotein convertase subtilisin/kexin type 9 (PCSK9) is an important factor in the etiology of familial hypercholesterolemia (FH) and is also an attractive therapeutic target to reduce low density lipoprotein (LDL) cholesterol." (PMID 20498851, 2010). "While evolocumab 420 mg monthly may represent a cost‐effective PCSK9 inhibitor option for Chinese hypercholesterolemia patients, further rigorous cost‐effectiveness analyses are warranted as well." (PMID 41585950, 2026).
Hypercholesterolemia (continued). "As the first PCSK9 inhibitor to be approved globally, evolocumab has not only offered an entirely novel therapeutic option for patients with familial hypercholesterolemia but also established a paradigm for the development of subsequent anti-PCSK9 monoclonal antibodies." (PMID 42256395, 2026). "Additionally, new-generation drugs such as PCSK-9 inhibitors offer hope for improving the HRQoL in patients with hypercholesterolemia by allowing for less frequent dosing and providing a greater effectiveness." (PMID 39941398, 2025). "These newly identified Nbs hold promise for their ability to target PCSK9 and could prove useful as treatments for hypercholesterolemia in the future." (PMID 39875480, 2025). "Although several reviews on PCSK9 inhibitors derived from natural products have been reported, they typically focused on specific disorders, such as atherosclerosis, hypercholesterolemia, and cardiovascular diseases, or reviewed the mechanisms associated with these diseases." (PMID 40942107, 2025). "PCSK9 was selected as the liver gene target because its editing attenuates hypercholesterolemia." (PMID 39415058, 2025). "Additionally, PCSK9 expression in the kidney exacerbates hypercholesterolemia in nephrotic syndrome and impairs megalin-mediated protein reabsorption in CKD, thereby aggravating proteinuria." (PMID 40289090, 2025). "PCSK9 has been identified as a protein associated with both CAD and hypercholesterolemia." (PMID 40868095, 2025). "However, in the liver, PCSK9 binds to and degrades the low-density lipoprotein receptor, which is a major contributor to hypercholesterolemia." (PMID 40535770, 2025). "We report the case of a 72-year-old man with a history of atrial fibrillation, hypertension, and refractory hypercholesterolemia who developed a fixed drug eruption following treatment with inclisiran, a small interfering RNA (siRNA) targeting proprotein convertase subtilisin/kexin type 9 (PCSK9)." (PMID 41510415, 2025). "Owing to their ability to bind and inhibit PCSK9, these Nbs may be promising therapeutic candidates for treatment or prevention of hypercholesterolemia." (PMID 39875480, 2025). "LDL-receptor protein is degraded by proprotein convertase subtilisin or kexin type 9 (PCSK9): LoF mutations in PCSK9 protect against CVD, whereas GoF mutations are associated with hypercholesterolemia and accelerated CVD57–59, demonstrating the critical role of this pathway." (PMID 41102563, 2025). "Furthermore, targeting PCSK9 to enhance its methylation has been proposed as a therapeutic strategy for hypercholesterolemia." (PMID 40606021, 2025). "While dietary counseling was provided as an immediate intervention, optimal management of familial hypercholesterolemia typically requires pharmacological therapy including statins, ezetimibe, and in severe cases, PCSK9 inhibitors or antisense oligonucleotides such as mipomersen." (PMID 41189009, 2025). "Ezetimibe is reserved for patients who do not achieve adequate lipid lowering or who are intolerant to statins, while PCSK9 inhibitors are strictly restricted to individuals with familial hypercholesterolemia or established cardiovascular disease who meet specific eligibility criteria." (PMID 40868833, 2025).
Hypercholesterolemia (continued). "This review discusses whether patients’ genotype affects the efficacy of PCSK9 inhibitors in treating familial hypercholesterolemia and how this might influence clinical management." (PMID 37610687, 2025). "The VT-1001 trial (NCT05398029) is a phase-1b clinical trial assessing the safety of a CRISPR-based therapy using base editing to disrupt the PCSK9 gene in the liver, aiming to reduce PCSK9 and LDLc in patients with heterozygous familial hypercholesterolemia and uncontrolled coronary heart disease." (PMID 40725677, 2025). "Evolocumab is the first monoclonal antibody against proprotein convertase subtilisin/kexin type 9 approved in Japan for familial hypercholesterolemia (FH) and hypercholesterolemia; however, data on its safety and effectiveness in the real‐world setting in Japan are limited." (PMID 39470058, 2024). "The variant's in silico analysis predicted the removal of several miRNA binding sites that could justify the observed hypercholesterolemia through a mechanism based on PCSK9 upregulation." (PMID 40225943, 2024). "Recent studies have proved that decreasing PCSK9 expression via endogenous RNA interference is a promising therapeutic approach to acutely reducing LDLc and have paved the way for the development of novel PCSK9 lowering agents for the management of severe hypercholesterolemia." (PMID 38445291, 2024). "Treatment based on PCSK9 elimination may therefore not only be a treatment for hypercholesterolaemia, but also a treatment for atherosclerosis and other cardiovascular diseases." (PMID 38886277, 2024). "Indeed, a few proprotein convertase subtilisin/kexin type 9 modulators have been implemented in the therapy for hypercholesterolemia." (PMID 38338741, 2024). "Importantly, PCSK9 inhibition is effective in patients with various forms of dyslipidemia, underscoring the ubiquitous role of PCSK9 in hypercholesterolemia." (PMID 39094771, 2024). "Considering most of the patients with hypercholesterolemia are in the older age group with multiple comorbidities, including renal dysfunction, PCSK9 inhibitors like evolocumab and alirocumab would be helpful in such cases, as monoclonal antibodies are relatively safe in renal dysfunction." (PMID 39439648, 2024). "Ezetimibe, a cholesterol absorption inhibitor that targets uptake at the jejunal enterocyte brush border, can be used alternatively or in combination with statins, while PCSK9 inhibitors such as Evolocumab and Alirocumab, are indicated in familiar hypercholesterolemia." (PMID 39596098, 2024). "MiR-99a-5p could serve as an inhibitor of PCSK9 for treating hypercholesterolemia to inhibit atherosclerosis." (PMID 39628814, 2024). "Likewise, genetically-determined aberrant expressions of PCSK9, another member of the proprotein convertase subtilisin/kexin family, have been correlated with hereditary hypercholesterolemia, severe steatosis and cardiovascular abnormalities." (PMID 38846491, 2024). "Thus, suppressing PCSK9 expression level has become an effective approach for treating hypercholesterolemia." (PMID 39628814, 2024). "The elimination of PCSK9 may, therefore, not only be a treatment for hypercholesterolaemia but also for atherosclerosis and other cardiovascular diseases." (PMID 38886277, 2024). "In addition, the high availability of glucose in tumor tissues fosters PCSK9 elevated secretion, which favors, in turn, hypercholesterolemia." (PMID 38846491, 2024).
Hypercholesterolemia (continued). "Similarly, many clinical studies have shown increased serum PCSK9 levels upon administration of statins in hypercholesterolemia patients." (PMID 39566851, 2024). "In addition, selected patients with very high LDL-C levels (>3.4 mmol/L) or familiar hypercholesterolemia can be administered upfront combined lipid-lowering medications including ezetimibe or a PCSK9 inhibitor." (PMID 39795963, 2024). "However, the precise molecular mechanism responsible for the statin-mediated increase in the PCSK9 expression remains elusive, and understanding this would shed more light on statin intolerance and resistance in hypercholesterolemia patients." (PMID 39566851, 2024). "Following the discovery that PCSK9 gain-of-function mutations were associated with familial hypercholesterolemia and loss-of-function mutations led to reduced levels of low-density lipoprotein cholesterol (LDL-C), PCSK9 rapidly became one of the most promising targets for modulating LDL-C levels." (PMID 38689297, 2024). "In addition, PCSK9 is another gene related to familial hypercholesterolemia and cardiovascular health that is attracting growing attention as a potential target to treat patients at high risk of CVD." (PMID 38247511, 2024). "Consequently,the PCSK9 inhibition is a valuable therapeutic approach for the treatmentof hypercholesterolemia and cardiovascular diseases." (PMID 37261954, 2023). "In addition to monoclonal antibodies, a new promising drug for treating hypercholesterolemia via PCSK9 mechanism has been recently approved for clinical use." (PMID 37745244, 2023). "On the other hand, the discovery and understanding of the function of proprotein convertase subtilisin/kexin type 9 (PCSK9) enzyme in lipid metabolism has led to the development of PCSK9 inhibitors to treat hypercholesterolemia and atherosclerotic cardiovascular disease." (PMID 37762360, 2023). "As soon as PCSK9′s role in cholesterol homeostasis had been discovered, there appeared interest to create therapies targeting its pathway which could be used in hypercholesterolemia treatment." (PMID 36831039, 2023). "PCSK9 inhibitors traditionally used to control hypercholesterolemia by reducing LDL-C." (PMID 36771126, 2023). "In the present study, we proposed a model-based methodology for the selection of an optimal repertoire of events for a composite endpoint, based on a meta-regression of historical data of anti-hypercholesterolemia therapies, including statins as well as anti-PCSK9 mAbs and siRNA." (PMID 38304061, 2023). "Therefore, PCSK9 inhibitors can be considered as an alternative lipid-lowering therapy for patients with hypercholesterolemia, especially for those with statin intolerance or resistance." (PMID 36834701, 2023). "Therefore, inhibition of PCSK9 is clinically useful for treatment of hypercholesterolemia, and inhibitors of PCSK9 have been FDA-approved as cholesterol-lowering therapeutics." (PMID 37351276, 2023). "Moreover, another study showed that PCSK9 concentrations were also high in patients with hypercholesterolemia." (PMID 37892538, 2023).